ACE (angiotensin I converting enzyme)
Diseases named in the same sentence as ACE in open-access papers (continued):
Sharing a sentence is not in itself a finding about the gene and the disease.
heart disease (continued). "Only underlying heart disease (NICM vs. ICM) and the use of ACE inhibitor were significant predictors of response to CRT-upgrade." (PMID 33320290, 2021). "Genetic differences in the angiotensin converting enzyme (ACE) have been shown to affect the way dogs respond to ACE-inhibitors, a class of medication which is used to treat dogs with heart disease." (PMID 34256860, 2021). "The major finding of our study is that oral administration of STS via the drinking water ameliorates L-NNA-induced heart disease to the same extent as ACE inhibition." (PMID 33935760, 2021). "Itwas stratified by disease severity, demonstrating a higher prevalence of ACE I/Dpolymorphism in the severe form of heart disease with HF." (PMID 32638886, 2020). "To date, the most commonly used therapy targeting the RAAS system to treat heart disease in children is ACE inhibitors." (PMID 31632936, 2019). "Observations in patients with cardiogenic shock and with ACE inhibitor use suggests a potential role for Ang II in patients with ACE depletion, either from acute ACE inhibitor overdose or as part of chronic heart disease management." (PMID 29282149, 2017). "A systematic review of ARBs and ACE inhibitors in ischaemic heart disease concluded that dual RAS inhibition with an ARB and ACE inhibitor is no better than ACE inhibitor or ARB therapy alone and increases the risk of harm." (PMID 23866091, 2013). "For example in another study it was found that two of the indicators considered actually reduced overall costs to the NHS (CHD 10- aspirin in heart disease and DM 15- ACE inhibitor drugs in diabetic renal disease)." (PMID 22507660, 2012). "However, all six patients presented a severe heart disease and the 50% of these were under treatment with ACE inhibitors or sartans." (PMID 40898253, 2025). "Understanding these confounding variables may help explain contradictory findings of previous studies of ACE inhibitors in dogs with heart disease, and is critical to the design of future studies." (PMID 36412252, 2023). "Indeed, in patients with established heart disease on long term ACE inhibitor therapy, bradykinin induced plasma tPA activity similar to those seen with systemic thrombolytic therapy." (PMID 33672724, 2021). "Both of these cardiac diseases are commonly treated with ACE-inhibitors." (PMID 34256860, 2021). "For patient characteristics of smoking status; family history of premature heart disease; and the use of beta-blockers, ACE inhibitors, and the aldosterone antagonists spironolactone and eplenerone, <30% of studies were closely matched to the reference population." (PMID 30564701, 2018). "ACE inhibitors are among the most commonly used antihypertensive drugs that have been demonstrated to be safe and to reduce mortality from heart disease, indicating that they would be the drug of choice for the treatment of hypertensive individuals with high early-life DDT exposure." (PMID 27325568, 2016). "Thus, the prevention of skeletal muscle fibrosis using early and continuous ACE inhibitor treatment in heart disease patients may play a role in muscle function." (PMID 32334642, 2020). "It is thus possible that combining RA, which specifically inhibits Ace1 expression, with ACE inhibitors may have synergistic beneficial effects in protecting cardiomyocytes post-MI, an interesting prospect for future studies aimed at improving the survival of patients suffering from heart disease." (PMID 34623260, 2021). "Surprisingly, no ACE-inhibitors or angiotensin-II-antagonists were included in any pattern, although most guidelines recommended them for cardiac diseases as first-line therapy." (PMID 34132623, 2021). "Again, these changes are reversed following treatment with ACE inhibitors or AT1 receptor blockers suggesting that the balance of ACE and ACE2 in the heart is an important driving factor for progressive cardiac disease." (PMID 22536270, 2012).
heart disease (continued). "In general, patients treated with ACE inhibitors before start of the current episode of AF had more evidence for heart disease than those who were not pre-treated." (PMID 15667649, 2005). "The genetic heterogeneity of the ACE gene and the nonuniversal occurrence of ABT in dogs could be an explanation for discordant outcome findings of previous studies reporting the long‐term effects of ACE‐inhibitors in dogs with heart disease." (PMID 32112596, 2020).
metabolic disorders (31 papers, 2009 to 2025). "A growing body of literature argues for a beneficial impact of ACE inhibitors (ACEi) on age-associated metabolic disorders, mediated by cellular changes in reactive oxygen species (ROS) that improve mitochondrial function." (PMID 30373167, 2018). "ACE, a central component of the renin–angiotensin system, links cardiovascular regulation with metabolic disorders." (PMID 41464892, 2025). "These peptides promise to play a role in preventing and treating metabolic diseases due to their dual inhibitory effects on ACE and DPP-IV." (PMID 38575133, 2024). "Future studies will focus on the in vivo therapeutic effect of such nanonutraceuticals to inhibit DPP-IV and ACE and test their behavior to modulate the cholesterol metabolism pathway for targeting the metabolic diseases." (PMID 35203539, 2022). "Upregulation of the ACE-Ang-II-AT1 R axis and downregulation of the ACE-2-Ang-1-7-Mas axis occur in metabolic disorders and also with age." (PMID 35433495, 2022). "Tests on the action of Undaria pinnatifida (wakame) on blood pressure and other metabolic disorders in hypertensive patients have shown the presence of ACE inhibitory peptides in a peptic digest, which may be responsible for the observed blood pressure reduction in these patients." (PMID 36827143, 2023). "Furthermore, when these peptides were entrapped within the RADA16 hydrogel, they were released slowly allowing their interaction with the DPP-IV and ACE catalytic sites, suggesting that this strategy could be a viable platform for targeting metabolic diseases." (PMID 35203539, 2022). "For metabolic disorders, Prunella vulgaris L.-derived sRNA, XKC-sRNA-h3, modulates angiotensin-converting enzyme (ACE) expression across species, eliciting antihypertensive effects." (PMID 40362513, 2025). "Previous studies focused on the vasoconstrictor arm of the RAS (ACE/AngII/AT1R) in rodents, illustrating that females are protected from cardiovascular and metabolic disorders produced by AGT, renin, and angiotensin II, as compared to males." (PMID 35629915, 2022). "Because of these responses, the ACE2/Ang 1–7/Mas axis counteracts the deleterious effect of ACE/Ang II/AT1R axis and has been investigated as a target for reducing metabolic diseases and CVD." (PMID 33178033, 2020). "It was showed that the WAT expresses the components of the renin angiotensin system (RAS), including angiotensin converting enzyme (ACE), angiotensin II (Ang II) and AT1 receptor (ACE/Ang II/AT1 axis), which is hyperactivated in metabolic diseases." (PMID 31022246, 2019).
retinopathy (28 papers, 2010 to 2025). "Both ACE and Ang II increases the level of vascular endothelial growth factors leading to abnormal retinal angiogenesis and increased risk of retinopathy and its progression." (PMID 26310144, 2015). "The EUCLID Study enrolled the diabetic patients observed that the angiotensin converting enzyme (ACE) inhibitor lisinopril reduced the risk of progression of retinopathy by approximately 50%, and also significantly reduced the risk of progression to proliferative retinopathy." (PMID 30460043, 2018). "Studies by other groups showed that the deletion in the ACE gene was associated with the prevalence of proliferativeretinopathy in type 1 diabetic patients suggesting that the DD genotype may increase the risk of proliferative retinopathy." (PMID 34177375, 2021). "Thus it also seems that in the Pakistani diabetics although ACE ID polymorphism is involved in the development of retinopathy but probably other factors such as angiogenic pathway e.g. VEGF etc. are involved in disease progression to the more severe form i.e. PDR." (PMID 26658948, 2015). "ACE levels were found elevated in type 2 diabetic patients, particularly in patients with retinopathy." (PMID 34177375, 2021). "Beyond of above factors, genetic gene polymorphisms obtained more attentions about the pathophysiological process leading to proliferative retinopathy in recent studies, such as ACE I/D, AGT M/T gene." (PMID 29484134, 2018). "It is reasonable to predict that ACE level could elevate in T2DM patients accompanied by retinopathy." (PMID 36992775, 2022). "In addition, the higher level of ACE in patients with proliferative retinopathy indicates a potential role of ACE in retinal vascular damage for DR." (PMID 29484134, 2018). "Results obtained in the Pakistani population therefore suggest a probable role of ACE in the development of the disease at early stages of retinopathy (NPDR), which is in contrast to the other studies, where significant association was found with advanced stages of retinopathy i.e. PDR." (PMID 26658948, 2015). "The high level of renin and ACE in diabetic patients could lead to an excess of angiotensin II in the eyes, and elevate local intravascular blood pressure to hasten the development of retinopathy." (PMID 29484134, 2018). "In fact, 155 patients (54 with DR, 101 with diabetic non-retinopathy, DNR) were determined with ACE genotypes and 133 (48 with DR, 85 with DNR) with AGT genotypes due to the loss of blood samples." (PMID 29484134, 2018). "The level of ACE in both serum and tear did not demonstrate a statistically significant correlation with the grade of retinopathy." (PMID 41189776, 2025). "In this study, we reported that the relationship between ACE, AGT gene polymorphism and T1DM subjects with retinopathy was not significant and the results were still consistent after adjusting for confounding factors." (PMID 29484134, 2018). "were more often treated with hypolipidemics (P < 0.01) and ACE-inhibitors (P < 0.01) than patients with no retinopathy (group 1); this was observed by Scheffe's post hoc test with test significance of 1%." (PMID 24696683, 2014).
respiratory disease (17 papers, 2009 to 2025). "Elevated tissue ACE levels are associated with increased risk for cardiovascular and respiratory disorders." (PMID 27734897, 2016). "Elevated ACE levels are associated with different cardiovascular and respiratory diseases." (PMID 23560051, 2013). "Thus, elevated ACE levels may be associated with an increased risk for different cardiovascular or respiratory diseases." (PMID 21998728, 2011). "CF patients with a homozygous deletion in the ACE gene (D/D genotype) tend to experience severe, early-onset respiratory disease and increased inflammation, while patients without this deletion (I/I genotype) generally exhibit better lung function due to reduced ACE activity." (PMID 40733537, 2025). "Among people without identified respiratory disease, chronic cough was more common in males, current smokers, participants with high levels of psychological disturbance, and fair to poor general health, and in those using ACE inhibitors." (PMID 20003540, 2009).
neurodegenerative disease (12 papers, 2015 to 2025). A disorder of the central nervous system characterized by gradual and progressive loss of neural tissue and neurologic function. "In this way, we elucidate the complex interplay between ACE and AD and assess the potential effect of ACE inhibition on neurodegenerative disease risk more widely." (PMID 36046424, 2022). "This approach enables us to identify a genetic proxy for the effect of ACE inhibitors that cross the blood-brain barrier and explore its association with risk of AD and other neurodegenerative diseases in a MR paradigm." (PMID 36046424, 2022). "Therefore, it is imperative to understand any potential long-term effect of ACE modulation on risk of later life neurodegenerative diseases." (PMID 36046424, 2022). "To further explore the relationship between ACE and neurodegenerative diseases, we advance previous work by performing 3-way colocalization analyses for ACE gene expression in the cortex, systolic blood pressure (SBP), and AD risk." (PMID 36046424, 2022). "Therefore, RAS inhibition by AT1 receptor antagonists or ACE inhibitors that are commonly used as anti-hypertensive drugs will be potentially able to prevent neurodegenerative diseases." (PMID 30934759, 2019). "While ACE inhibition may counteract these effects, some clinical studies have reported short-term cognitive benefits from ACEIs in early Alzheimer’s cohorts, underscoring the need for the context-specific evaluation of RAAS modulation in neurodegenerative disease management." (PMID 40722848, 2025).
neurological diseases (11 papers, 2017 to 2025). "The neurological diseases have a strong association with ACE, MTHFR, and TNF." (PMID 34947975, 2021). "The results showed that the focus genes for target and digestive system cancers were ACE, PTGS2, CYP2C19, and CYP2A6, while the number of intersections with neurological diseases was 73, and the three shared a focus on ACE, PTGS2 and CYP2C19 (top left)." (PMID 37701374, 2023). "Recently, it was suggested that inhibition of ACE/Ang II/AT1 axis or activation of ACE/Ang II/AT1 axis is considered as a potential target for treatment of neurological diseases." (PMID 37854465, 2023). "We discovered that 3 out of the 105 AD genes were shared by all five neurological disorders: ACE, MTHR, and TNF." (PMID 28553317, 2017). "The FCTF model of the local medicinal food Laoxianghuang focuses on the efficacy of digestive system cancers and neurological diseases, with key targets ACE, PTGS2, CYP2C19 and corresponding active components citronellal, trans-nerolidol, linalool, geraniol, α-terpineol, cadinene and α-pinene." (PMID 37701374, 2023). "Interestingly, three AD genes (ACE, TNF, and MTHFR) were associated with all four of the other neurological diseases." (PMID 28553317, 2017).
kidney (8 papers, 2013 to 2025). "The results of this study confirm and extend our previous work that acute kidney injury with STNx leads to impaired renal function, increased cortical ACE activity and reduced ACE2 activity in the medulla and cortex." (PMID 25786223, 2015). "Previous studies by our group have demonstrated that excess mitochondrial superoxide generation observed in the diabetic kidney is not affected by current clinically used therapies such as ACE inhibitors." (PMID 25367693, 2014). "In fact, an increase in ACE activity, not accompanied by a corresponding rise in ACE2 locally, was also observed in the diabetic kidney, which was considered a key driver of renal injury." (PMID 40650071, 2025).
psychiatric disorder (8 papers, 2013 to 2025). A disorder characterized by behavioral and/or psychological abnormalities, often accompanied by physical symptoms. "Taken together, ACE polymorphisms can be regarded as risk factors for a variety of psychiatric disorders." (PMID 35606706, 2022). "Further assessment of expression levels of ACE in the circulation of these patients is necessary for confirming the association between these polymorphisms and risk of psychiatric disorders." (PMID 35606706, 2022). "Cumulatively, the current data support involvement of two polymorphisms of ACE gene in conferring risk of diverse psychiatric disorders." (PMID 35606706, 2022). "Moreover, substance P as a neuropeptide substrate for ACE may contribute in the etiology of psychiatric disorders such as schizophrenia (SCZ) and bipolar disorder (BPD)." (PMID 35606706, 2022). "Long-term therapy includes ACE inhibitors or ARB, hormone replacement wherever required in postmenopausal women, and combined psycho-cardiac rehabilitation when psychiatric disorders exist." (PMID 39201162, 2024). "Emerging evidence highlights the role of angiotensin I-converting enzyme (ACE), which is the main enzyme of the renin-angiotensin system (RAS), in the pathogenesis of neurological and psychiatric disorders." (PMID 35741861, 2022).
bacterial infections (6 papers, 2020 to 2024). "Collectively, our findings of ACE+ MΦs reflect the multitude of factors that shape MΦ phenotypes and their functions during persistent intracellular bacterial infection." (PMID 36608122, 2023). "In transgenic mice who overexpress ACE, there is increased resistance to bacterial infections through elevated production of superoxide which in turn increases NET formation and cytokine release." (PMID 35508575, 2022). "In contrast to ACE KO, NeuACE mice show enhanced resistance to bacterial infections as compared to WT mice." (PMID 32508938, 2020). "It was found that ACE upregulation increased NO production in macrophages leading to an improved immune response to bacterial infection." (PMID 32508938, 2020). "While ACE expression in Mtb granulomas had been well described, whether ACE+ MΦs are a distinct subset of MΦs in granulomas and what their functions are during persistent intracellular bacterial infection remain unknown." (PMID 36608122, 2023). "Inhibition of ACE suppresses neutrophil immune response to bacterial infection." (PMID 32508938, 2020). "However, whether ACE+ MΦs are a functionally distinct population of granuloma MΦs and what role they play during persistent intracellular bacterial infections remain unknown." (PMID 36608122, 2023). "Enhanced expression of ACE in CD115+ myelomonocytic cells (ACE10 or ACE10/10 model) improve their ability to mediate an effective immune response to remove viral and bacterial infections, cancer growth, and atherosclerotic plaques." (PMID 37427403, 2023). "A human pilot study observed decreased resistance of human neutrophils toward bacterial infection after short-term ACE inhibitor (ACEi) usage, but not angiotensin receptor blockers (ARBs)." (PMID 39000163, 2024). "The role of ACE+ MΦs during persistent intracellular bacterial infections has not been defined." (PMID 36608122, 2023). "Our single-cell transcriptomics enable delineation of MΦ phenotypes in granulomas and infected tissues during persistent intracellular bacterial infection that have not been defined, such as the bone marrow–derived VCAM-1+ granuloma MΦ population and ACE+ granuloma MΦ population." (PMID 36608122, 2023).
genetic diseases (4 papers, 2009 to 2024). "We envision that these improved ACE-tRNA expression cassettes will allow for a therapeutic approach for a wider range of nonsense-associated genetic diseases." (PMID 39673265, 2024).
peripheral neuropathy (4 papers, 2015 to 2025). A disorder affecting the peripheral nervous system. "Some preclinical data has revealed that RAS inhibitors, such as angiotensin-converting enzyme (ACE) inhibitors and angiotensin receptor blockers (ARB), exert a neuroprotective effect in various murine models of peripheral neuropathy, potentially via angiotensin II type 2 receptor stimulation." (PMID 35629066, 2022).
inflammation (2 papers, 2016 to 2022). Aberrant reaction of the microcirculation characterized by movement of fluid and leukocytes from the blood into extravascular tissues. "High levels of circulating ACE are associated with pulmonary inflammation, and ACE is also highly expressed by endothelial cells composing the pulmonary microvasculature." (PMID 35913450, 2022). "Specifically, inhibition of ACE decreased the cellular inflammatory response in experimental models of lung inflammation." (PMID 26909880, 2016).
myopathy (2 papers, 2023 to 2024). A disease of the muscle in which the muscle fibers do not function properly. "For instance, the concurrent use of simvastatin and amlodipine increased the risk of myopathy, while the combination of allopurinol and ACE inhibitors like captopril enhanced the potential for toxicity." (PMID 38817515, 2024).